OR5AR1 (olfactory receptor family 5 subfamily AR member 1)
Description:
Odorant receptor.
Synonyms: OR11-209
Tractability: Antibody: UniProt places it where antibodies can reach, with medium confidence; UniProt predicts a signal peptide or a membrane-spanning region; its Gene Ontology location is reachable by antibodies, with medium confidence.
Gene: Protein-coding gene on chromosome 11 (56,663,686 to 56,664,618, forward strand). Ensembl gene ENSG00000172459.
Subcellular location: Cell membrane
Pathways (Reactome):
Sensory Perception: Expression and translocation of olfactory receptors
Gene Ontology:
Molecular function: odorant binding; olfactory receptor activity; copper ion binding; G protein-coupled receptor activity
Biological process: sensory perception of smell; detection of chemical stimulus involved in sensory perception; detection of chemical stimulus involved in sensory perception of smell; G protein-coupled receptor signaling pathway
Cellular component: plasma membrane; membrane
Genetic constraint (gnomAD): Loss-of-function variants: 16 observed, 13.25 expected, observed/expected ratio (o/e) 1.21, 90% interval 0.81 to 1.77. The upper end of that interval is the gene's LOEUF score, 1.77, which puts it in group 6 of 6, group 1 being the genes least tolerant of losing a copy. Missense variants: 408 observed, 370.45 expected, observed/expected ratio (o/e) 1.1, 90% interval 1.01 to 1.2. Synonymous variants: 148 observed, 139.87 expected, observed/expected ratio (o/e) 1.06, 90% interval 0.93 to 1.21.
Homologues: Orthologues: dog OR5AR1 (93% identical), rabbit OR5AR1 (93% identical), mouse Or5ar1 (93% identical), rat Or5ar1 (93% identical), chimpanzee OR5AR1 (92% identical), macaque OR5AR1 (88% identical). Paralogues in human: OR5B12 (57% identical), OR5B21 (57% identical), OR5C1 (56% identical), OR5W2 (55% identical), OR5AS1 (55% identical), OR8U1 (55% identical), OR8U3 (55% identical), OR9H1 (53% identical), OR5AP2 (53% identical), OR5AU1 (53% identical), OR5M10 (53% identical), OR5F1 (52% identical), and 84 more.